INS (insulin)
Diseases named in the same sentence as INS in open-access papers (continued):
Sharing a sentence is not in itself a finding about the gene and the disease.
diabetes (continued). "On the eighth day of hospitalization, the patient was transferred to a general ward and adjustments for diabetes medications and insulin doses were made." (PMID 40859516, 2025). "Longer diabetes duration, higher frequency of insulin use and higher BUN were observed in both the A2 and A3 groups, when compared with the A1 group (all p < 0.05)." (PMID 39806776, 2025). "Anthocyanins exhibit promising effects on glucose homeostasis, insulin sensitivity, and oxidative stress, presenting a potential avenue for preventing and managing diabetes." (PMID 39136514, 2025). "Glucose control improved from the beginning and in three out of six patients with cortisol-induced diabetes it was possible to withdrawn insulin therapy during etomidate infusion." (PMID 39694989, 2025). "These 21 functions were validated at a seminar, and two example functions, empowering people with diabetes who use insulin to manage their diabetes and arranging self‐administration of insulin in hospital, were discussed in detail." (PMID 40696540, 2025). "Diabetes mellitus (DM) is defined as a group of metabolic disorders characterized by chronic hyperglycemia resulting from defects in insulin secretion, insulin action, or both." (PMID 40804870, 2025). "Diabetes mellitus (DM) is a group of metabolic diseases characterised by hyperglycaemia resulting from defects in insulin secretion, insulin action, or both." (PMID 40827222, 2025). "Despite new drugs and technologies in diabetes therapy, hypoglycaemia remains a significant acute complication in people using insulin and insulin‐releasing therapy." (PMID 40818105, 2025). "PA was a protective factor against the incidence of DR, both in univariate analysis and after multifactorial (age, sex, duration of diabetes, glycaemic control, control of blood pressure, insulin, smoking, drinking, AVR, and PAVR) correction." (PMID 41343177, 2025). "Patients with diabetes mellitus also frequently develop hypomagnesemia, which has been attributed to diabetic hyperfiltration and the interaction of insulin in downregulating TRPM6 activity and expression." (PMID 40740723, 2025). "The selection criteria for diabetes included self-reported diabetes, on anti-diabetes drugs, taking insulin, fasting glucose ≥110mg/dl, or glycohemoglobin (HbA1c) ≥6.5%." (PMID 40978650, 2025). "Nurse practitioners were more likely to prescribe newer diabetes medications, while physician assistants frequently prescribed basal insulin." (PMID 39802219, 2025). "Diabetes distress was also higher among insulin users (B 7.6, 95% CI 5.4–9.7), and among people with a history of diabetes foot ulcers (B 9.3, 95% CI 5.3–13.2)." (PMID 39972441, 2025). "The results demonstrated that GIP antagonism for 50 days significantly improved insulin sensitivity and facilitated the reversal of glucose intolerance and diabetes." (PMID 40214973, 2025). "We also examined METTL14 expression in blood samples from 20 people with diabetes before and after intensive insulin therapy." (PMID 40299682, 2025). "This canonical model for coupling glucose sensing with insulin secretion was established by studies of normal physiology as well as of monozygotic forms of diabetes." (PMID 39936989, 2025). "Diabetes classification, disease duration, and insulin exposure duration were significantly correlated with EIAS occurrence." (PMID 41585798, 2025). "Impaired insulin secretion contributes to the pathogenesis of type 1 diabetes mellitus through autoimmune destruction of pancreatic β-cells and the pathogenesis of severe forms of type 2 diabetes mellitus through β-cell dedifferentiation and other mechanisms." (PMID 39883142, 2025). "Baseline characteristics of insulin users in HPACC survey, showing overall among all countries regardless of sample size, and the subset of countries with N > 100 people with diabetes reporting insulin use." (PMID 40245017, 2025).
diabetes (continued). "Each group expressed distinct priorities: patients with breast cancer focused on treatment burden, patients with diabetes highlighted challenges related to insulin, and patients with COPD emphasized autonomy in managing respiratory symptoms." (PMID 40583599, 2025). "In individuals with metabolic syndrome or diabetes, low-intensity endurance exercise prescribed at Fatmax enhanced body composition and insulin sensitivity." (PMID 41590220, 2025). "Pharmacological inhibition of HSP90AA1 in mice with diabetes or diet-induced obesity and IR improves insulin sensitivity through the activation of HSF1, a key regulator of stress response." (PMID 40004184, 2025). "A meta-analysis of randomized trials found that replacing animal protein with plant protein, including legumes, modestly improved HbA1c, fasting glucose, and insulin in people diagnosed with diabetes." (PMID 41305580, 2025). "This reflects broader metabolic consequences and underlines mitochondrial bioenergetics as an attractive target for therapeutic strategies aimed at enhancing insulin secretion and countering diabetes-related pathologies." (PMID 41440034, 2025). "All four probands were born to unaffected parents, had low birthweight (Z‐score range − 4.72 to −1.90) and were diagnosed with insulin‐treated diabetes at a median age of 1 week (range: 1 day–52 weeks)." (PMID 39509107, 2025). "Older age, longer duration of diabetes mellitus, insulin therapy and comorbid hypertension were significantly associated with poor glycemic control among the study population." (PMID 40078898, 2025). "Skipping breakfast impairs physiological insulin secretion, leading to disruptions in glucose homeostasis, which can contribute to the onset of diabetes." (PMID 41404108, 2025). "High blood pressure and insulin-requiring diabetes mellitus were identified in the INTERHEART Study." (PMID 39756819, 2025). "Type I and II diabetes mellitus are among these systemic diseases; they are characterized by hyperglycemia resulting from insufficient insulin secretion, impaired insulin action, or a combination of both." (PMID 41010847, 2025). "Variants in the genes GCK, HNF1A, HNF1B, HNF4A, ABCC8, INS, and INSR were the main contributors to the genetic pathogenesis of hereditary diabetes mellitus in the Russian cohort." (PMID 39859454, 2025). "Whilst remission of diabetes seems an attractive goal, improvement in metabolic parameters and reduction in medication use, especially insulin, are also potentially valuable outcomes of ILI programmes that are relevant at later stages of type 2 diabetes." (PMID 40707395, 2025). "The patient’s preference for premixed insulin (Humalog 50) with fewer daily injections underscores the importance of individualised diabetes management and patient-centred care." (PMID 40918801, 2025). "In Arkansas, 16 GO terms related to diabetes, glucose cycling, insulin cycling or weight gain were enriched among genes containing outlier loci." (PMID 41208600, 2025). "The ASC inflammasome stands as a pivotal player in the onset of diabetes, intricately linking chronic inflammation to the troubling phenomena of insulin resistance and pancreatic dysfunction." (PMID 41296433, 2025). "PR polysaccharides significantly reduce blood glucose and serum glycosylated hemoglobin concentrations in mouse models of diabetes, whereas they increased streptozotocin-induced insulin expression in diabetic rats." (PMID 41295268, 2025). "These medications were determined to be indicative of the respective frailty factor: insulin for diabetes, levothyroxine for thyroid disease, and levodopa-carbidopa for Parkinsonism." (PMID 40336214, 2025). "As the global prevalence of diabetes continues to rise, largely driven by increasing rates of obesity, sedentary lifestyles, and poor dietary habits, the effective management of insulin secretion and sensitivity becomes imperative for a healthy life." (PMID 40806100, 2025).
diabetes (continued). "Diabetes mellitus (DM) is a chronic metabolic disorder characterized by high blood sugar levels due to impaired insulin production or function." (PMID 40342454, 2025). "About 90% of all cases of diabetes are type 2, which is defined by variable levels of insulin resistance and/or inadequate insulin production in cells." (PMID 40641385, 2025). "CM works in two main ways to combat diabetes: first, CM appears to protect and improve the function of pancreatic β-cells, helping the incretion of the appropriate amount of insulin." (PMID 41007307, 2025). "Responses were categorized into 4 groups based on the extent of reimbursement for diabetes technologies and insulin." (PMID 40864470, 2025). "The DMPK gene encodes a serine-threonine kinase that is closely related to other kinases involved in the insulin secretion pathway, which helps explain the diabetes observed in P5." (PMID 41614819, 2025). "Despite this low affinity for (rodent) insulin self-antigen, mAb125 supports diabetes in NOD mice when it is expressed as a BCR transgene, showcasing the pro-pathogenic potential of low-affinity anti-insulin BCRs." (PMID 41259806, 2025). "This complements the traditional focus on achieving euglycemia with advanced insulin analogs and insulin delivery technologies, offering a broader strategy for improved diabetes management." (PMID 41234236, 2025). "Technological advances in glucose monitoring and insulin delivery are enhancing the modern therapeutic management of diabetes." (PMID 39496965, 2025). "Intensive glycemic control using insulin has been shown to mitigate both microvascular and macrovascular complications in individuals diagnosed with type 1 diabetes mellitus (T1DM)." (PMID 40093018, 2025). "Sirtuins play a crucial role in diabetes by regulating key metabolic processes, including hepatic glucose homeostasis, pancreatic β-cell insulin secretion, skeletal muscle metabolic balance, adipocyte energy regulation, and insulin sensitization, among others." (PMID 40705152, 2025). "In this case, appetite suppression, along with GLP-1RA-induced inhibition of gluconeogenesis and glycogenolysis, was thought to have contributed to reduced insulin administration and the subsequent development of ketoacidosis." (PMID 40507203, 2025). "Insulin-specific CD8+ T cells play a pivotal role in the pathogenesis of diabetes in both murine models and humans." (PMID 41373714, 2025). "In diabetes, impaired insulin signaling in the RPE contributes to retinal damage, highlighting the importance of this pathway for retinal health." (PMID 41301488, 2025). "Continuous glucose monitoring (CGM) offers a detailed view of glycaemic management, potentially enhancing the effectiveness of non‐insulin, anti‐diabetes medications." (PMID 40851538, 2025). "After applying LASSO regression, six risk factors, including gender, daily drinker, current smoker, disease history of diabetes, usage of insulin and cholesterol lowering medication were excluded from the final prediction model." (PMID 40181326, 2025). "Conventional treatment of diabetes involves the administration of insulin and oral hypoglycemic drugs, such as sulfonylureas, biguanides, and glinides." (PMID 41302106, 2025). "The positive effects of using metal ions for the treatment of diabetes were reported in 1899, prior to the discovery of insulin by Lyonnet and coworkers, who observed lowered glucose levels when using sodium metavanadate." (PMID 40286074, 2025). "In managing diabetes, insulin injection (N = 116, 30%), physical exercise (N = 75, 19%), oral medication (N = 69, 18%), diet control (N = 68, 18%), or herbal/traditional remedies (N = 57, 15%) were used by the participants." (PMID 41030747, 2025). "The degree of HbA1c improvement in our study was comparable to studies on smartphone-based diabetes management platforms and a larger trial on an automated insulin titration system." (PMID 39924297, 2025).
diabetes (continued). "Research has shown that STAT3 can regulate diabetes by controlling hepatic glucose metabolism, including gluconeogenesis and glycolysis, as well as insulin sensitivity." (PMID 40733369, 2025). "Recently, insulin and glucose infusion were implemented during emergency off-pump coronary artery bypass grafting in a patient with type 2 diabetes mellitus who received empagliflozin 2 days prior to surgery; the patient did not develop perioperative euDKA." (PMID 40855351, 2025). "Proteins exclusively expressed in prediabetes/diabetes were assigned to a Reactome pathway related to zinc transporter and insulin processing." (PMID 39941463, 2025). "Diabetes mellitus is largely driven by oxidative stress that disrupts insulin signaling, leading to failure in insulin-mediated glucose absorption." (PMID 41227734, 2025). "Type 2 diabetes mellitus (T2DM) only develops when insulin secretion is insufficient to compensate for insulin resistance." (PMID 41373994, 2025). "As a result, this study was designed to evaluate the extent of adherence to insulin therapy among patients with diabetes attending ambulatory care, along with identifying key barriers to adherence to insulin therapy." (PMID 39854487, 2025). "Compared to sex- BMI-matched nonsurgical controls, individuals who underwent a BarS procedure showed lower mean levels of total cholesterol, LDL-C, triglycerides, fasting glucose, and insulin as well as lower prevalences of diabetes and MetS." (PMID 40989870, 2025). "For instance, CD–insulin complexes in pH-sensitive hydrogels have demonstrated on-demand insulin release under hyperglycemic conditions, representing a potential breakthrough for diabetes management." (PMID 40733310, 2025). "The relationship between insulin sensitivity and insulin secretion is pivotal in the progression to AGT/diabetes; however, there is a strong need for efficient tools to evaluate this relationship." (PMID 39611962, 2025). "This review elucidates the molecular mechanisms by which PCs improve insulin sensitivity and endothelial health, thereby providing protection against the various complications of diabetes." (PMID 39995417, 2025). "Dysregulation of insulin signaling can trigger metabolic diseases such as diabetes, which is characterized by either insufficient insulin production or an impaired response to insulin." (PMID 40867533, 2025). "Resveratrol dramatically alleviates hyperglycemia and has a beneficial impact on insulin sensitivity in diabetes animal models generated by STZ or alloxan injection." (PMID 40035065, 2025). "Overall, 52,394 CGM‐naïve adults with non‐insulin‐treated type 2 diabetes using anti‐diabetes medications were identified (4086 CGM users; 48,308 CGM non‐users)." (PMID 40851538, 2025). "Functionally, GLP-1R activation by its endogenous agonist GLP-1 promotes insulin secretion, suppresses glucagon release, slows gastric emptying, and induces satiety, thereby making it a pivotal therapeutic target in type 2 diabetes mellitus (T2DM) and obesity." (PMID 41226200, 2025). "The expression of insulin in the retina was altered with the progression of diabetes in streptozotocin-induced diabetic models in mice and donors with DR." (PMID 41301488, 2025). "The dysregulation of insulin signalling, such as in insulin resistance and diabetes, can lead to hyperglycaemia and complications like cardiomyopathy." (PMID 40243689, 2025). "This study investigates the relationship between insulin–glucose homeostasis, diabetes mellitus and the haptoglobin concentration in HS patients." (PMID 40217596, 2025). "In diabetes mellitus, these signals can be dysregulated via one or several of the proteins driving insulin signaling (AKT1, PIK3R1, INSR, PPARG, and PIK3CG)." (PMID 41011980, 2025). "Drug therapy is always recommended by clinicians once lifestyle intervention is unsatisfactory, insulin or oral hypoglycemic drugs against diabetes, and statin against hyperlipidemia." (PMID 40066222, 2025).
diabetes (continued). "Animal models of type 1 diabetes mellitus (T1DM) and type 2 diabetes mellitus (T2DM) demonstrated distinct skeletal alterations, largely attributed to differences in insulin availability and associated metabolic dysfunction." (PMID 40564223, 2025). "To investigate how Lnk functions affect the susceptibility to diabetes, we used STZ, a selective cytotoxic agent against insulin-generating pancreatic β cells, resulting in β cell apoptosis and autoimmune diabetes." (PMID 41027725, 2025). "The β-cell UPRER is also engaged in monogenic forms of diabetes, such as mutant insulin-induced diabetes of youth (MIDY), where mutations in the INS gene cause misfolding of the insulin protein, leading to activation of UPRER and β-cell dysfunction." (PMID 40950193, 2025). "In diabetes mellitus, OMVs impair insulin signaling and hepatic glycogen synthesis through gingipain-mediated disruption of the Akt/GSK-3β pathway." (PMID 40791780, 2025). "In endocrinology, verapamil has emerged as a compelling candidate for preserving β-cell function in diabetes, with clinical trials confirming its ability to reduce insulin requirements and hypoglycemic episodes in type 1 diabetes." (PMID 40710367, 2025). "In contrast, the misinformation statement “patients with diabetes on insulin cannot exercise” was the least shared, with only 4.7% of participants endorsing it." (PMID 40724794, 2025). "Chronic overproduction of RNS, notably ONOO−, plays a critical role in the pathogenesis of diabetes by inducing mitochondrial dysfunction and OS, particularly in insulin‐sensitive tissues such as skeletal muscle and adipose tissue." (PMID 40599237, 2025). "Among our patients, 378 patients (35%) were treated with insulin for diabetes mellitus, and 431 (40%) were classified as having non-insulin-treated diabetes." (PMID 41153651, 2025). "The intervention included insulin titration and regular follow-up with the trained diabetes nurse for diabetes care and management." (PMID 40161188, 2025). "For the treatment of diabetes mellitus various synthetic oral hypoglycemic drugs and insulin is available." (PMID 40828850, 2025). "Another limitation lies in the characteristics of the study population, which limits results generalizability to datasets including subjects with different characteristics (e.g., insulin-treated diabetes)." (PMID 40648295, 2025). "Study selection: We selected articles that compared the GWG in women with diabetes treated with metformin or insulin." (PMID 41098669, 2025). "In a clinical study, the combination of Astragalus decoction pieces with conventional therapy showed positive effects on insulin secretion function and insulin resistance in type 2 diabetes mellitus (T2DM) patients." (PMID 40453655, 2025). "While programs that focus on lifestyle interventions in T2D patients sometimes show decreases in weight, studies with people with diabetes who are treated with insulin usually indicate weight stability over time." (PMID 40661654, 2025). "Tailored diabetes education is a fundamental component in the successful initiation and maintenance of insulin pump therapy in children and adolescents with T1D." (PMID 40887640, 2025). "Skin-implantable devices have revolutionized glucose management in patients with diabetes by integrating continuous glucose monitoring and automated insulin delivery systems." (PMID 40863003, 2025). "Diabetes is a chronic disease characterized by high glucose levels together with impairment of insulin levels/activity." (PMID 40943066, 2025). "Despite insulin therapy and the use of oral drugs, including α-glucosidase inhibitors that are commonly used to alleviate hyperglycemia and treat diabetes, natural compounds found in plants play a significant role in the prevention and treatment of T2DM." (PMID 41375221, 2025).